PIK3CA (phosphatidylinositol-4,5-bisphosphate 3-kinase catalytic subunit alpha)
Diseases named in the same sentence as PIK3CA in open-access papers (continued):
Sharing a sentence is not in itself a finding about the gene and the disease.
breast cancer (continued). "Our data suggest that HER2-positive breast cancers with activating mutations in PIK3CA are less likely to benefit from pyrotinib combined with trastuzumab neoadjuvant therapy." (PMID 36323880, 2023). "In contrast to previous studies on human breast cancer, we observed a higher frequency of PIK3CA mutations in patients with low ESR1 and PGR expression." (PMID 38033642, 2023). "With the recent approval of a specific PIK3CA inhibitor for breast cancer patients whose tumors harbor PIK3CA mutations or have PIK3CA mutations in their ctDNA, the proficiency testing for PIK3CA mutation analysis was initiated both for tissue and LB samples." (PMID 36367572, 2023). "In another study, the combined inhibition of BCL-XL and mTOR was found to synergistically induce apoptosis in PIK3CA-mutated breast cancer." (PMID 36588105, 2023). "Oncogenic mutations of PIK3CA (PIK3CAmut) are signature mutations in multiple cancers, which are present in approximately 30% of human breast cancer patients, and at a higher proportion in LBC patients, especially in refractory advanced disease." (PMID 37965796, 2023). "In this study, genes in PIK3/AKT/mTOR pathway were deciphered, and PIK3CA mutations were identified as the most frequent genetic alterations observed in 38% of Taiwanese patients with breast cancer." (PMID 37655108, 2023). "Alpelisib (targeting the PI3K catalyst subunit α or PI3KCA) and everolimus (targeting mTOR) are already approved by the FDA for the treatment of HR-positive, HER2-negative breast cancers (with a PIK3CA mutation for alpelisib)." (PMID 37759706, 2023). "PIK3CA mutations are among the most frequently seen genetic changes in breast cancer, occurring in about 25–45% of cases." (PMID 37096065, 2023). "Common breast cancer mutations in the PIK3CA, GATA3 and KMT2C genes are significantly more prevalent in ER-positive/HER2-negative/low proliferation/luminal A cancers compared to the claudin-low group." (PMID 37345027, 2023). "As PIK3CA is known to be one of the major driver oncogenes, the discovery of activating PIK3CA mutations has been elucidated in multiple cancers, including breast cancer, cervical cancer and lung cancer." (PMID 37965796, 2023). "In HER2+/PIK3CA mutated breast cancer cell lines, alpelisib was more potent than trastuzumab or trastuzumab + pertuzumab in inhibiting the in vitro growth and the combination of alpelisib plus trastuzumab also showed synergistic activity." (PMID 37469415, 2023). "In the preclinical setting, HER2+ breast cancer cell lines harboring PIK3CA mutations are resistant to trastuzumab and retain AKT phosphorylation despite treatment." (PMID 37469415, 2023). "According to TCGA, PIK3CA (coding mutations in 40.1% of the samples) dominated the mutation landscape of breast cancer." (PMID 37715134, 2023). "Given the well-known role of GOF PIK3CA mutations as a driver oncogene in reproductive cancers, particularly breast cancer, we conducted a comparative meta-analysis to highlight any genetic similarities shared between these cancers and vascular anomalies." (PMID 37109059, 2023). "The canine PIK3CA gene mutated in 55% and 38% of benign and malignant mammary tumors, respectively, encodes for a 1068 amino acid protein that shares 99% similarity with its human counterpart." (PMID 37835752, 2023).
breast cancer (continued). "Among these, PI3K pan-inhibitors, buparlisib and taselisib have been shown to be particularly active in HER2+ breast cancer models with PIK3CA activating mutations." (PMID 37469415, 2023). "Phosphatidylinositol-4,5-bisphosphate 3-kinase catalytic subunit alpha (PIK3CA) is a well-known oncogene with a high prevalence of mutation in breast cancer patients." (PMID 37761256, 2023). "Mutations in PIK3CA are present in 28–46% of people with hormone receptor (HR)-positive – HER2-negative advanced breast cancer." (PMID 38025526, 2023). "While this breast cancer subtype has low PIK3CA mutation rates when compared to estrogen receptor-positive (ER+) breast cancers, most basal-like TNBCs have an overactive PI3K pathway due to gene amplification or high gene expression." (PMID 36900375, 2023). "PIK3CA mutations have also been found to be associated with the response to breast cancer treatment." (PMID 37237509, 2023). "PIK3CA mutations have also been observed more frequently in the luminal type than in the basal-like breast cancers." (PMID 36323880, 2023). "From breast cancer actionability, PIK3CA (ESCAT Tier IA) was reported in 39.4% (n = 97), AKT1 mutation (ESCAT Tier IIB) in 45.9% (n = 113), and ERBB2 mutation (ESCAT Tier IIB) in 17.1% (n = 42) of early-stage Taiwanese breast cancers." (PMID 37760445, 2023). "In xenograft mice models of PIK3CA mutant breast cancer and PTEN-deficient prostate cancer, the excessive activation of the PI3K-AKT-mTOR signaling protects cancer cells from LPO and ferroptosis by SREBP1/SCD1-mediated MUFA synthesis." (PMID 37700339, 2023). "Our findings enhance the understanding of how PIK3CA mutations shape the clinical and prognostic landscape for breast cancer patients." (PMID 37761256, 2023). "The PIK3CA activation mutation is among the most common oncogenic mutations described in breast cancer to date." (PMID 36773078, 2023). "Among HER2-positive breast cancers, approximately 20% harbor a PIK3CA mutation that is associated with resistance to trastuzumab-based therapy." (PMID 36913051, 2023). "PIK3CA gene encoding the p110 catalytic subunit of PI3K is most frequently mutated in luminal breast cancer." (PMID 37106324, 2023). "Consistent with previous studies, we identified a high prevalence of PIK3CA mutations in 38% of the Taiwanese patients with breast cancer." (PMID 37655108, 2023). "To further identify optimal tumor contexts susceptible to bi-steric mTORC1-selective inhibition we focused on breast cancers where this pathway is commonly activated by mutation in upstream regulators such as PIK3CA and PTEN." (PMID 37264081, 2023). "In early stage breast cancer patients, the presence of PIK3CA mutation was associated with a better disease-free survival and overall survival." (PMID 37344660, 2023). "Two rigorous research letters reported that H1047R mutation in PIK3CA induces multipotency and multi-lineage mammary tumours, and induced multipotency in unipotent progenitors." (PMID 36323880, 2023). "The phosphoinositide 3-kinase (PI3K)-protein kinase B (AKT) pathway is active in most breast cancers, and 40% of ER+ breast cancers are associated with PIK3CA mutation, which is a common genomic alteration in breast cancer." (PMID 36671478, 2023). "The most frequently mutated isoform in cancer is PIK3CA, whose mutations are an early event in colon and breast cancer." (PMID 36765661, 2023).
breast cancer (continued). "For example, Breast carcinoma patients with variant PIK3CA p.Glu453Lys are sensitive to the FDA-approved therapy Alpelisib + Fulvestrant based on the result of a Phase III clinical trial SOLAR-1 (NCT02437318)." (PMID 36856726, 2023). "PIK3CA gene mutations are known as a good prognostic factor for breast carcinoma, and a poor prognostic marker for colorectal tumors." (PMID 37483495, 2023). "The presence of PIK3CA mutations represents an independent adverse prognostic factor in breast carcinoma and has been associated with more aggressive disease and poor outcomes in metastatic disease." (PMID 36825198, 2023). "Approximately 40% of estrogen receptor-positive (ER+)/HER2-breast carcinomas have mutations in the PIK3CA gene, leading to hyperactivation of the alpha isoform (p110α) of phosphatidylinositol-3-kinase (PI3K)." (PMID 36825198, 2023). "The use of Therascreen® is not widespread in Portugal, but multiple technologies and platforms are available for molecular testing, which can potentially be used to detect PIK3CA mutational status in HR+/HER2-breast carcinoma samples." (PMID 36825198, 2023). "A recent study including a large number of metastatic breast carcinomas (n = 3871) confirmed these data, reporting the presence of PIK3CA mutations in 39% of HR+/HER2- and 37% of HER2-amplified tumors, besides 21% of triple-negative carcinomas." (PMID 36825198, 2023). "Copanlisib (BAY 80-6946) and pictilisib (GDC-0941) induced tumor regression in a rat HER2-amplified PIK3CA-mutated and murine HER2 amplified PIK3CA-mutated breast cancer models, respectively." (PMID 36046843, 2022). "Findings from the BYLieve Cohort C updated analysis support the clinical benefit of alpelisib plus fulvestrant in patients with HR-positive, HER2-negative, PIK3CA-mutated advanced breast cancer who were treated primarily in the third-line setting." (PMID 35348782, 2022). "For example, CNAs are associated with poor survival in breast cancer patients; mutations in PIK3CA are associated with poor survival in certain estrogen receptor (ER)-positive breast cancers." (PMID 36584096, 2022). "Both ddPCR and BEAMing have been shown to be able to detect PIK3CA mutations in plasma ctDNA from patients with breast cancer." (PMID 35565189, 2022). "PIK3CA is the most frequently mutated gene in luminal breast cancer and the same hotspot mutations present in MCF7 and T47D have been found in 45% of patient tumors, underlining the clinical relevance of the model systems in our study." (PMID 35625984, 2022). "PTEN loss or PIK3CA mutations are common oncogenic events in HER2+ breast cancer, occurring in approximately 19% and 42% of patients, respectively." (PMID 35800378, 2022). "The current study found that IL3RA has considerable significance in the prognostic risk model of leukemia, while PIK3CA in breast cancer." (PMID 35769153, 2022). "As clinical relevant result, we demonstrated resistance of early breast cancer with somatic PIK3CA-mutation to adjuvant aromatase inhibitor therapy, suggesting tamoxifen as preferred therapy in these patients." (PMID 36279023, 2022). "The mutation list is highly similar to the finding in breast cancer of unspecified genotypes (PIK3CA H1047R E545K N345K, and AKT1 E17K)." (PMID 36298462, 2022). "We tested this model in the context of heterozygous mutations in PIK3CA, the most frequently mutated gene in breast cancer." (PMID 35676284, 2022).
breast cancer (continued). "Because approximately 40% of patients with HR-positive, HER2-negative breast cancer also have the PIK3CA mutation, alpelisib–fulvestrant is an effective therapeutic combination for targeted therapy, especially for cancers with endocrine resistance." (PMID 35216405, 2022). "The U.S. Food and Drug Administration (FDA) has already approved its use in combination with fulvestrant for treating postmenopausal women with ER+/HER2-, PIK3CA-mutated breast cancer that has progressed after hormone therapy." (PMID 36332545, 2022). "PIK3CA is a gene frequently mutated in breast cancer, and its mutations have been a key target of therapeutic research in cancer, with the clinical trials of PI3K pathway inhibitors presently underway." (PMID 36672784, 2022). "PIK3CA mutations are the most common in breast cancer, particularly in the estrogen receptor-positive cohort, but the benefit of PI3K inhibitors has had limited success compared with approaches targeting other less common mutations." (PMID 35676284, 2022). "Evidence has demonstrated that NECB has different mutational profiles from other ER-positive and HER2-negative breast cancers with a lower frequency of PIK3CA mutations and a higher mutation rate in other genes." (PMID 35692784, 2022). "Tucatinib is an orally bioavailable tyrosine kinase inhibitor that is approved for HER2-positive MBC, while the phosphoinositide-3-kinase (PI3Kα) inhibitor alpelisib is approved for HER2-negative, PIK3CA-mutated advanced breast cancer." (PMID 36145265, 2022). "Given the role of PIK3CA in breast cancer pathogenesis and as a predictive biomarker as well, we performed a mutational analysis focused on the most (approximately 90%) common PIK3CA variants described in breast cancer." (PMID 35740668, 2022). "PIK3CA-BIRC5 was another reassuring pair as depletion of survivin (BIRC5) has been shown to have a pro-apoptotic effect in breast cancer cells with PIK3CA mutations." (PMID 36517508, 2022). "A phase II trial (NCT01776008) showed that MK-2206 did not increase the efficacy of anastrozole monotherapy in patients with PIK3CA-mutated ER+ breast cancer." (PMID 36010585, 2022). "Results from the more recent phase 2 BYLieve study indicate that alpelisib in combination with endocrine therapy (fulvestrant or letrozole) is also effective in patients with HR+, HER2–, PIK3CA-mutated breast cancer in the post-CDK4/6 inhibitor setting." (PMID 35406370, 2022). "Combination therapy comprising the SERM fulvestrant and the PI3Kα inhibitor alpelisib was recently approved for advanced ER+ breast cancers that harbor PIK3CA mutations." (PMID 36612130, 2022). "Compared with the Western cohort, the mutation frequency of PIK3CA in breast cancer was reduced in the Chinese cohort." (PMID 35778737, 2022). "Activating PIK3CA mutations are found in 20% of HER2+ breast cancers and have been described as a mechanism of resistance to some HER2-directed therapies." (PMID 36010990, 2022). "Approximately 25% of breast cancer patients with PIK3CA mutations, which is one of the most common genetic aberrations in breast cancers, are ER-positive." (PMID 35735430, 2022). "The phosphatidylinositol-3 kinase catalytic alpha (PIK3CA) gene is one of the most frequent somatic mutations in breast cancer." (PMID 35719907, 2022). "In this report, we provide guidance for hyperglycemia management and monitoring strategies aimed at minimizing alpelisib dose disruption in patients with HR+, HER2−, PIK3CA-mutated advanced breast cancer." (PMID 35406370, 2022). "In HR‐positive/HER2‐negative breast cancer, PIK3CA is one of the most commonly mutated genes, and is also more prevalent among patients in China than in western countries." (PMID 38089455, 2022).
breast cancer (continued). "Although the vast majority of mutations in PIK3CA are single mutations, 12–15% of breast cancers have multiple mutations in the gene." (PMID 35055414, 2022). "The results indicated that GDC-0084 is a potential compound in brain metastatic mammary neoplasms with a dysregulativity of PI3K/mTOR signals conferred by PIK3CA mutations." (PMID 36539659, 2022). "FTY720 was effective in trastuzumab-resistant breast cancer cell lines despite the presence of PIK3CA mutation." (PMID 34997132, 2022). "PIK3CA mutation has been reported in 20%–40% of breast cancers, but the incidence differs across breast cancer subtypes." (PMID 35016012, 2022). "Specifically, certain CMT subtypes, such as PIK3CA mutated, estrogen receptor-positive simple carcinomas, can be valuable in setting up a preclinical model highly relevant to human breast cancer research." (PMID 36302863, 2022). "The NCCN breast cancer clinical practice guidelines recommended that Alpelisib plus fulvestrant combination therapy should be used as the first choice for the treatment of HR + /HER2- breast cancer patients carrying PIK3CA mutations." (PMID 35778737, 2022). "Alpelisib selectively inhibits the PI3Kα isoform and its effectiveness against tumors harboring PIK3CA mutations was initially established in several early phase studies, testing the combination of alpelisib with ET in patients with ER+ breast cancer." (PMID 36046843, 2022). "PIK3CA mutations are found in nearly all neoplasm types, such as mammary tumors, colorectal carcinoma, esophageal cancer, gallbladder carcinoma, non-small cell lung cancer (NSCLC), ovarian cancer, and gastric carcinoma." (PMID 36539659, 2022). "While the regulatory subunit p85 has three isoforms p110α, p110β and p110δ, p110α is encoded by PIK3CA gene that is considered one of the most frequently mutated genes in cancers, particularly in breast cancer." (PMID 35778737, 2022). "The p110α specific inhibitor Alpelisib in combination with Fulvestrant has been approved by the FDA for the treatment of HR-positive and HER2-negative breast cancers with PIK3CA mutation." (PMID 35418124, 2022). "In this study, we propose to develop a deep convolutional neural network (DCNN) to identify PIK3CA mutations in breast cancer based on US images." (PMID 35719907, 2022). "Accordingly, determining the PIK3CA mutation status of breast cancer patients is critical to the management." (PMID 35719907, 2022). "The PI3Kα/γ/δ inhibitor, taselisib, in combination with fulvestrant, exhibits clinical benefit for metastatic ER+ breast cancers associated with multiple PIK3CA mutations." (PMID 36612130, 2022). "For example, CLEOPATRA (Clinical Evaluation of Pertuzumab and Trastuzumab) test proved that the mutate of PIK3CA was a prognostic factor for patients with advanced HER2 positive breast cancer." (PMID 36699089, 2022). "PIK3CA is a major driver gene of breast cancer with well-defined hotspot mutations, thus showing that our genome-wide machine learning models of CA and RT can capture known driver genes." (PMID 35947558, 2022). "In summary, we show that differential expression between the mutant and wild-type alleles of PIK3CA is common in breast cancer and with a significant contribution from allele-specific cis-regulatory effects." (PMID 35676284, 2022). "Among patients with early breast cancer, PIK3CA mutations were associated with better invasive disease-free survival, but not distant disease-free survival or overall survival." (PMID 36131248, 2022). "In this study, we proposed a DCNN-ImResNet using non-invasive US images to identify PIK3CA mutation status for patients with breast cancer." (PMID 35719907, 2022). "In this study, to our knowledge we present the largest analysis of PIK3CA oncogenic mutations to date, using an unselected routine cohort of early stage breast cancer patients (n = 1123)." (PMID 36279023, 2022).